KLKP1 (kallikrein pseudogene 1 )
Synonyms: KARMA; KLK31P; KRSP1; PsiKLK1; YKLK1
Gene: Long non-coding RNA gene on chromosome 19 (50,882,096 to 50,896,398, reverse strand). Ensembl gene ENSG00000290915.
Diseases named in the same sentence as KLKP1 in open-access papers:
KLKP1 is named in the same sentence as 3 diseases in open-access papers, as found by Europe PMC text mining. Sharing a sentence is not in itself a finding about the gene and the disease. The quoted sentences say what the papers report.
prostate carcinoma (3 papers, 2012 to 2021). A carcinoma that arises from epithelial cells of the prostate gland. "The unique feature of the KLK4-KLKP1 fusion gene is the conversion of the non-coding KLKP1 pseudogene into the gene encoding the protein and its unique expression in about 30% of high-grade Gleason prostate cancer." (PMID 34947885, 2021). "Expression analysis of KLK4, KLK4T2, and KLKP1 transcripts in prostate cancer cell lines showed high levels of KLKP1 transcripts in the nucleus and in unfractionated cell extract, whereas it was almost completely absent in the cytoplasmatic fraction." (PMID 34884832, 2021). "The closest validated gene to the KLK4 3′ end is the Kallikrein family pseudogene KLKP1, thus these SNPs may regulate the activity of this pseudogene or expression of KLKP1 transcripts, which have been shown to be down-regulated in prostate cancer tissues." (PMID 22970239, 2012).
KLKP1 also shares sentences with these, for which no sentence is quoted: renal cell carcinoma (2 papers); tumor (1).